ALDH6A1 (aldehyde dehydrogenase 6 family member A1)
Diseases named in the same sentence as ALDH6A1 in open-access papers (continued):
Sharing a sentence is not in itself a finding about the gene and the disease.
cancer (12 papers, 2017 to 2024). A tumor composed of atypical neoplastic, often pleomorphic cells that invade other tissues. "ALDH6A1 is a mitochondrial aldehyde dehydrogenase which has been associated with drug metabolism in cancer." (PMID 37591798, 2023). "Extensive clinical analyses have shown that the decreased expression of ALDH6A1 is correlated to tumorigenesis and inferior outcomes in different kinds of cancers, which may serve as a potential diagnostic and prognostic biomarker." (PMID 36694633, 2023). "Taken together, our results reveal that the common residues at positively selected sites in ALDH6A1 of long‐lived mammals offer an enhanced function in resisting cancer progression." (PMID 37395176, 2023). "The potential mechanisms of the association of low ALDH2 with cancer aggressiveness include the possible interaction with another member of the ALDH family, ALDH6A1, based on the gene and protein co-expression network analysis." (PMID 37476181, 2023). "Downregulation of ALDH6A1 implicates the initiation and progression of different types of cancer." (PMID 37476181, 2023). "This not only evidenced that ALDH6A1 overexpression could inhibit growth and migration of cancer cells, but also indicated the ALDH6A1 of long‐lived mammals show stronger inhibition of cellular migration of cancer cells." (PMID 37395176, 2023). "What’s more, ALDH6A1 and its isozymes were broadly correlated with cancers, implying that ALDH6A1 could be used for therapeutic targets." (PMID 36098688, 2022). "ABAT and ALDH6A1 have similar expression profiles in cancers." (PMID 32093682, 2020). "Moreover, ALDH6A1 has been reported to be involved in the process of cancers." (PMID 36098688, 2022).
metabolic disorders (5 papers, 2015 to 2025). "Increased ALDH6A1 activity affected the metabolism of BCAAs and propionate, leading to an increase in downstream propionyl-CoA, which in turn changed protein propionylation levels and causing metabolic disorders." (PMID 40467924, 2025).
infection (2 papers, 2009 to 2010). The state of being infected such as from the introduction of a foreign agent such as serum, vaccine, antigenic substance or organism. "Several aldehyde dehydrogenases are up-regulated during infection, especially ALDH6A1, a liver mitochondrial enzyme that catalyzes the breakdown of malonate to propionyl – and acetyl-CoA, (up-regulated 37- and 22-fold in pre-viremic and viremic stages)." (PMID 19216742, 2009).
ALDH6A1 also shares sentences with these, for which no sentence is quoted: prostate carcinoma (3 papers); epilepsy (2); Insulin resistance (2); bladder urothelial carcinoma (1); colon adenocarcinoma (1); diabetes mellitus Type 1 (1); Encephalopathy (1); esophageal carcinoma (1); head and neck squamous cell carcinoma (1); Hyperammonemia (1); hyperlipidemia (1); hyperprolinemia (1); hyperprolinemia type 2 (1); lymph node metastasis (1); metastatic disease (1); microcephaly (1); pyridoxine-dependent epilepsy (1); Sjögren-Larsson syndrome (1); thymoma (1); type 2 diabetes mellitus (1).